TRAV26-1 (T cell receptor alpha variable 26-1)
Description:
V region of the variable domain of T cell receptor (TR) alpha chain that participates in the antigen recognition. Alpha-beta T cell receptors are antigen specific receptors which are essential to the immune response and are present on the cell surface of T lymphocytes. Recognize peptide-major histocompatibility (MH) (pMH) complexes that are displayed by antigen presenting cells (APC), a prerequisite for efficient T cell adaptive immunity against pathogens. Binding of alpha-beta TR to pMH complex initiates TR-CD3 clustering on the cell surface and intracellular activation of LCK that phosphorylates the ITAM motifs of CD3G, CD3D, CD3E and CD247 enabling the recruitment of ZAP70. In turn ZAP70 phosphorylates LAT, which recruits numerous signaling molecules to form the LAT signalosome. The LAT signalosome propagates signal branching to three major signaling pathways, the calcium, the mitogen-activated protein kinase (MAPK) kinase and the nuclear factor NF-kappa-B (NF-kB) pathways, leading to the mobilization of transcription factors that are critical for gene expression and essential for T cell growth and differentiation. The T cell repertoire is generated in the thymus, by V-(D)-J rearrangement. This repertoire is then shaped by intrathymic selection events to generate a peripheral T cell pool of self-MH restricted, non-autoaggressive T cells. Post-thymic interaction of alpha-beta TR with the pMH complexes shapes TR structural and functional avidity.
Synonyms: TCRAV26S1; TCRAV4S2; TRAV261
Gene: T-cell receptor variable (V) gene on chromosome 14 (22,123,318 to 22,124,285, forward strand). Ensembl gene ENSG00000211807.
Subcellular location: Cell membrane
Gene Ontology:
Biological process: response to bacterium
Cellular component: plasma membrane
Homologues: Paralogues in human: TRAV26-2 (64% identical), TRAV4 (59% identical), TRAV13-1 (26% identical), TRAV20 (26% identical), TRAV39 (26% identical), TRAV1-1 (25% identical), TRAV10 (25% identical), TRAV38-1 (25% identical), TRAV38-2DV8 (25% identical), TRAV21 (24% identical), TRAV17 (23% identical), TRAV30 (23% identical), and 11 more.
Diseases named in the same sentence as TRAV26-1 in open-access papers:
TRAV26-1 is named in the same sentence as 4 diseases in open-access papers, as found by Europe PMC text mining. Sharing a sentence is not in itself a finding about the gene and the disease. The quoted sentences say what the papers report.
breast carcinoma (1 paper, 2025). "Additionally, research has shown that MR1-restricted TRAV1-2+ and TRAV26-1+ TCRs identified from the tumor-infiltrating T cells of breast cancer patients specifically respond to some breast cancer cell lines but not to other cancer types." (PMID 40746558, 2025).
coeliac disease (1 paper, 2024). "Similar observations have been found in TCRs utilising the TRAV26-1 gene in coeliac disease (TCRs S16, D2, JR5.143) and in type I diabetes (TCRs A2.13, A5.5, A5.844 and TCRs ET600-1, ET650-1, -2, -3, -4, and -545)." (PMID 39043656, 2024).
TRAV26-1 also shares sentences with these, for which no sentence is quoted: cervical cancer (1 paper); type I diabetes (1).